YY1 (YY1 transcription factor)
Diseases named in the same sentence as YY1 in open-access papers (continued):
Sharing a sentence is not in itself a finding about the gene and the disease.
lipid metabolic disorder (3 papers, 2019 to 2025). "Various studies have demonstrated that YY1 is closely related to lipid metabolism disorders." (PMID 36330745, 2022).
liver fibrosis (3 papers, 2018 to 2025). "In the present study, we observed that YY1 acts as a transcription repressor to inhibit the expression of KIF18A, and uncovered a hitherto undocumented mechanism by which YY1 regulates liver fibrosis in HSCs." (PMID 38372748, 2024). "In the context of liver fibrosis, YY1 is aberrantly upregulated, resulting in the transcriptional suppression of KIF18A and its protein expression." (PMID 38372748, 2024). "FXR plays a key role in maintaining lipid metabolic homeostasis, regeneration of liver cells and prevention of liver fibrosis, while YY1 regulates lipid metabolism via the FXR-SHP signaling axis by targetting intron 1 of the FXR gene." (PMID 30429231, 2018). "Few prior studies have investigated the role of YY1 in liver fibrosis." (PMID 38372748, 2024). "Furthermore, we examined the expression of YY1 in fibrotic liver tissue and investigated its role in the pathogenesis of liver fibrosis." (PMID 38372748, 2024). "In summary, our study sheds light on the YY1/KIF18A/TTC3-signaling pathway and its effects on AKT/TOR, providing a basis for future research into liver fibrosis treatment." (PMID 38372748, 2024).
mesothelioma (3 papers, 2022 to 2024). A usually malignant and aggressive neoplasm of the mesothelium which is often associated with exposure to asbestos. "High expression of YY1 was related with poor prognosis of BLCA (P = 0.0027) and mesothelioma (MESO) (P = 0.026) in TCGA patients, according to disease free survival (DFS) study data." (PMID 35791393, 2022). "Therefore, despite the absence of YAP track in the Cistrome DB of A549 cells, we assume that YAP binds PTEN promoter since a YAP peak overlapping with TEAD4, YY1 and MYC is present in the mesothelioma cell line H2052." (PMID 39455556, 2024).
schizophrenia (3 papers, 2013 to 2025). A major psychotic disorder characterized by abnormalities in the perception or expression of reality. "Only one study reports that the missense schizophrenia risk variant rs1801311 (located in the 1st exon of NDUFA6 gene) can disrupt the binding of YY1, TAF1, and POLR2A." (PMID 36680208, 2023). "Our observation indicated that YY1 activated the expression of miR-141-3p, representing that it might play a momentous role in the pathogenesis of schizophrenia." (PMID 36680208, 2023). "There are almost no studies of the role of YY1 in schizophrenia." (PMID 36680208, 2023).
urothelial bladder cancer (3 papers, 2022 to 2025). "CAF-derived miR-146a-5p can promote stemness and enhance chemoresistance in urothelial bladder cancer via regulating YY1/SVEP1 and ARID1A/PRKAA2 signal pathways." (PMID 38737906, 2024).
Anxiety (2 papers, 2022 to 2023). Intense feelings of nervousness, tension, or panic often arise in response to interpersonal stresses. "In an attempt to explain how a unidirectional epigenetic alteration can underscore a bidirectional shift in anxiety phenotypes, the researchers honed in on a transcription factor Ying-Yang1 (YY1), which was reported to be bidirectionally expressed between HAB-EE and LAB-CMS mice." (PMID 35998298, 2023). "Having ascertained that CUS drives similar depressive- and anxiety-like phenotypes in male and female mice, we next assessed whether YY1 similarly functions in female PFC cortical neurons to control stress responses." (PMID 35013139, 2022). "We found that in vivo deletion of Yy1 in PFC excitatory neurons alone did not induce a robust depressive- and anxiety-like state in mice, as determined by the comparable sucrose preference and open field responses between YY1-KO males and YY1-exGFP controls." (PMID 35013139, 2022).
atherosclerosis (2 papers, 2024 to 2025). A disease characterized by the build-up of fatty material and calcium deposition in the arterial wall resulting in partial or complete occlusion of the arterial lumen. "In atherosclerosis, YY1 is upregulated in macrophages exposed to oxidized LDL (oxLDL), where it drives foam cell formation, lipid accumulation, and inflammatory gene expression." (PMID 41459495, 2025).
cerebral infarction (2 papers, 2019 to 2021). An ischemic condition of the brain, producing a persistent focal neurological deficit in the area of distribution of the cerebral arteries. "Moreover, ANRIL promotes inflammatory responses through activating NF-κB pathway and binding with Yin Yang 1 (YY1) in endothelial cells as well as cerebral infarction rat models." (PMID 31411246, 2019). "Overexpressed Smurf2 or downregulated YY1, HIF1α, or DDIT4 reduced the volume of cerebral infarction and apoptosis in MCAO mice, while enhancing cell viability and reducing apoptosis and lactate dehydrogenase leakage in OGD-treated neurons." (PMID 33722608, 2021).
colitis (2 papers, 2016 to 2025). Inflammation of the colon. "In a dextran sulfate-induced colitis model, YY1 was shown to reduce Foxp3 expression in Tregs, thereby inhibiting their suppressive function." (PMID 40458393, 2025). "YY1 is increased in Treg cells under inflammatory conditions with concomitant decrease of suppressor activity in dextran sulfate-induced colitis model." (PMID 26892542, 2016). "To further investigate physiological relevance of YY1 expression in Treg cells, we examined whether YY1 expression is modulated in Treg cells under an inflammatory condition using dextran sodium sulfate (DSS)-induced colitis model." (PMID 26892542, 2016).
developmental delay (2 papers, 2016 to 2025). "Mice heterozygous for the YY1 gene (yy1+/−) display a mild developmental delay and a subset of these animals exhibit neurulation defects and exencephaly." (PMID 26924789, 2016).
epilepsy (2 papers, 2016 to 2021). A brain disorder characterized by episodes of abnormally increased neuronal discharge resulting in transient episodes of sensory or motor neurological dysfunction, or psychic dysfunction. "The last two genes were newly discovered neurodevelopmental syndrome genes (LARP7 and YY1), which require more cases to summarize clinical characteristics and to update the epilepsy-associated gene lists." (PMID 34992632, 2021). "Subsequently, we detected strong epileptogenesis-induced dissociation of the repressive transcription factor YY1 from the Mmp-9 proximal promoter chromatin occurring at early stages of epilepsy development by ChIP." (PMID 27505431, 2016).
gastric tumors (2 papers, 2021 to 2022). "Furthermore, drugs capable of inhibiting YY1-mediated transcription have been identified as suitable targeted therapeutic candidates for gastric tumors." (PMID 35993308, 2022). "The presence of co-activation of TERT and YY1 was determined in a subset of gastric tumors." (PMID 34497757, 2021).
glaucoma (2 papers, 2020 to 2023). Increased pressure in the eyeball due to obstruction of the outflow of aqueous humor. "If the computational prediction is accurate, the glaucoma risk allele (rs6475604‐C) would increase p16INK4A expression by causing reduced binding of its repressor, YY1." (PMID 37345431, 2023). "NF-κB/YY1 signaling was reported to be associated with microglial activation in the progression of glaucoma, characterized with the progressive loss of retinal ganglion cells and optic nerve fibers." (PMID 32140464, 2020). "Furthermore, the segments CGCCATTTT and CGCCATTCT had relative binding affinities of 487.21 and 465.71, respectively (the higher values indicate stronger binders), demonstrating that the glaucoma risk fragment had reduced binding of YY1 as compared to the non‐risk allele." (PMID 37345431, 2023).
hyperandrogenism (2 papers, 2022). Excessive secretion of androgens from the adrenal glands or gonads. "For example, gene ontology and pathway analysis showed that dysregulated lncRNAs in GCs in PCOS with hyperandrogenism have a regulatory role in mitochondrial function by interacting with transcription factors such as yin-yang 1 (YY1) and SIX homeobox 5 (SIX5)." (PMID 36498989, 2022). "‐In ovarian granulosa cells from women with PCOS with or without hyperandrogenism‐dysregulated lncRNA in PCOS have a regulatory role in mitochondrial function via interacting with transcription factors such as YY1 and SIX5." (PMID 34989136, 2022).
hypertrophic cardiomyopathy (2 papers, 2020 to 2025). A condition in which the myocardium is hypertrophied without an obvious cause. "YY1 protein abundance significantly increases in failing human hearts and transgenic mice with hypertrophic cardiomyopathy." (PMID 39850120, 2025).
Intellectual Disability syndrome (2 papers, 2020 to 2025). "Genetic mutations of YY1 cause intellectual disability syndrome." (PMID 39747661, 2025).
ischemia (2 papers, 2019 to 2026). A hypoperfusion of the BLOOD through an organ or tissue caused by a PATHOLOGIC CONSTRICTION or obstruction of its BLOOD VESSELS, or an absence of BLOOD CIRCULATION. "Endothelial-specific deletion of YY1 leads to defective vascular regeneration following ischemia." (PMID 42159401, 2026).
laryngeal squamous cell carcinoma (2 papers, 2021 to 2022). A squamous cell carcinoma that arises from the larynx. "The current study aimed to elucidate the role and mechanism of YY1 in laryngeal squamous cell carcinoma (LSCC)." (PMID 34497757, 2021).
leishmaniasis (2 papers, 2025). Infectious disease that is transmitted through the bite of hematophagous female phlebotomine sand flies. "This study also explored the significance of YY1-dependent macrophage proteins beyond leishmaniasis, particularly in the context of infection and immunity." (PMID 40801584, 2025). "It was intriguing to investigate the significance of YY1-dependent macrophage proteins beyond leishmaniasis, particularly in the context of infection and immunity." (PMID 40373059, 2025). "Several known functions of YY1 that could impact the pathophysiology of leishmaniasis, likely favoring Leishmania persistence in host macrophages." (PMID 40801584, 2025). "Additionally, we analyzed the possible role of YY1 modulated proteins in infections other than leishmaniasis and in immunity." (PMID 40373059, 2025). "Several functions of YY1 could contribute to the pathobiology of leishmaniasis." (PMID 40801584, 2025).
liver disease (2 papers, 2021 to 2023). "Dysregulated YY1 has been reported to lead to dysregulated cellular metabolism including glycometabolism, lipid metabolism, and bile acid metabolism in the liver, which is believed to be one of the underlying mechanisms of how YY1 is involved in various liver diseases." (PMID 34099540, 2021). "Further studies are needed to elucidate the role of YY1 and its regulated TFs and coactivators in hepatic lipid metabolism and liver diseases, NAFLD and HCC in particular." (PMID 34099540, 2021). "Our study further proved that YY1 directly or indirectly regulates the expression of several important TFs and their coactivators in lipid metabolism, which provided novel insights into the molecular mechanisms associated with YY1 overexpression in NAFLD and other liver diseases." (PMID 34099540, 2021). "Recent studies suggested that dysregulated YY1 plays a pivotal role in many liver diseases." (PMID 34099540, 2021). "In addition to HCC, cumulative data indicate a pivotal role of YY1 in almost all other liver diseases, for example, hepatitis induced by virus infection, liver fibrosis, liver regeneration and both alcoholic liver disease and NAFLD." (PMID 34099540, 2021). "This may partially explain the observed dysregulation of YY1 in various liver diseases." (PMID 34099540, 2021).
lung squamous cell carcinoma (2 papers, 2022 to 2023). "In lung squamous cell carcinoma, keratin 5 type (IIKRT5) gene mutation can increase the expression of YY1." (PMID 35791393, 2022).
metastatic disease (2 papers, 2009 to 2015). "Moreover, in many human cancer types, YY1 expression levels were found to be significantly elevated in the metastatic tumor compared to its primary counterpart, supporting the potential role of YY1 in cancer development." (PMID 26104682, 2015). "By exploring the role of YY1 in migration and invasion, our study adds another layer to the complex role that YY1 may play in the development of metastatic disease." (PMID 19566924, 2009).
muscular dystrophy (2 papers, 2016 to 2022). Muscular dystrophy (MD) refers to a group of more than 30 genetic diseases characterized by progressive weakness and degeneration of the skeletal muscles that control movement. "This association suggests that YY1 may be disrupted in muscular dystrophy tissues." (PMID 27667448, 2016). "When YY1 was deleted in skeletal muscle satellite cells, the acute damage-induced muscle repair was blocked, resulting in muscular dystrophy." (PMID 36171891, 2022). "The fourth cluster contains a YY1 knockout (GSE39009) signature produced in mice soleus, and an autosomal muscular dystrophy signature from a mouse model sourced from the diaphragm (GSE3252)." (PMID 27667448, 2016).
myelogenous leukemia (2 papers, 2021 to 2025). "During oncogenic transformation to both hepatoblastoma and myelogenous leukemia, target genes of SEs that maintain YY1 binding during transformation have lesser changes in gene expression than SE target genes with which YY1 is not stably associated." (PMID 40502787, 2025). "Accumulated mutations and epigenetic changes in the HSC population have been associated with some types of myeloid leukemia; thus, detection of high expression levels of YY1 in some patients with myeloid leukemia cancers suggests that YY1 may play an oncogenic role." (PMID 33728560, 2021).
Parkinson’s (2 papers, 2020 to 2021). "In Parkinson’s Disease, YY1 is downregulated in microglia, along with other neuroprotective pathways like mTOR and TGF-β." (PMID 33102493, 2020). "YY1 regulates the expression of NRF2-mediated anti-oxidant response and the transmembrane transporter SVCT2-dependent import of the protective drug ascorbate, which are key targets for Parkinson’s disease treatment developments." (PMID 33102493, 2020).
prostate adenocarcinoma (2 papers, 2014 to 2023). "Clinical characteristics of prostate adenocarcinoma (PRAD) patients and Ying Yang 1 (YY1) expression in the Cancer Genome Atlas (TCGA) database." (PMID 37771187, 2023). "In addition, YY1 and DR5 gene expression from the prostate adenocarcinoma samples were analyzed in the same data sets and compared with the prostate gland." (PMID 25174820, 2014).
prostatic intraepithelial neoplasia (2 papers, 2012 to 2013). "Overexpression of YY1 has been detected by using immunohistochemical staining in a large series of PCa and prostatic intraepithelial neoplasia tissues." (PMID 23883094, 2013). "Increased YY1 levels are observed in prostatic intraepithelial neoplasia (PIN) and advanced disease." (PMID 22536409, 2012).
respiratory failure (2 papers, 2014 to 2020). The significant impairment of gas exchange within the lungs resulting in hypoxia, hypercarbia, or both, to the extent that organ tissue perfusion is severely compromised. "We have shown that, in mice, the tissue-specific Yy1 deletion with the sonic hedgehog (Shh)-Cre recombinase, which drives Cre activity in Shh-expressing tissues including the respiratory tract epithelium, causes death at birth due to respiratory failure." (PMID 33158935, 2020). "A dosage-dependent requirement for YY1 is essential for survival as newborn mice expressing 25% of normal YY1 levels die at birth from respiratory failure." (PMID 24705708, 2014).
skin cancer (2 papers, 2022 to 2023). "The staining pattern for YY1 on the skin tumours of K14-HPV8-CER mice indicated that YY1 intracellular distribution is switched from nuclear to cytoplasmic in the presence of HPV8 early proteins and may play a role in HPV8-induced tumorigenesis." (PMID 35406439, 2022). "As YY1 had been one of the predicted transcription factors, we analysed K14-HPV8-CER skin tumours for total levels of YY1 by immunohistochemistry." (PMID 35406439, 2022). "In basal keratinocytes of K14-HPV8-CER skin tumours, we observed no or only weak staining for YY1." (PMID 35406439, 2022).
skin melanoma (2 papers, 2022 to 2023). "Nevertheless, we found that 15% of uterine corpus endometrial carcinomas (UCEC) and 8% of skin melanomas (SKCM) harbored YY1 mutations." (PMID 37894300, 2023). "Together, our results suggest that PEBP1 and YY1 mutations associate with the infiltration of specific immune cells in skin melanoma and uterine corpus endometrial carcinomas, respectively." (PMID 37894300, 2023). "In skin melanoma cells, miR-625 directly targeted YY1 to suppress cell proliferation, migration, invasion, and EMT." (PMID 35992812, 2022).
squamous cell carcinoma (2 papers, 2020 to 2025). A carcinoma arising from squamous epithelial cells. "However, high YY1 expression only correlated with squamous cell carcinoma (SCC) patients, while high expression of ZNF322A, Shh, and CD31 (ZNF322Ahigh/Shhhigh/CD31high) tended to occur more frequently in adenocarcinoma (ADC) patients than in SCC patients." (PMID 32929330, 2020).
steatosis (2 papers, 2014 to 2020). Increased lipid within the cytoplasm of cells. "Many oncogenes, such as gankyrin, HBx, YY1, KrasV12, Xmrk, and Myc, have been shown to induce steatosis or HCC in zebrafish, and the tumors induced share many similar characteristics with human tumors." (PMID 24416389, 2014). "HFD feeding leads to the upregulation of Yin Yang 1 (YY1), which blocks FXR and thus promotes steatosis." (PMID 32443737, 2020).
tongue cancer (2 papers, 2018 to 2021). A malignant neoplasm affecting the tongue. "YY1 mRNA expression was upregulated in tongue cancer compared with that in the adjacent normal tissue." (PMID 29970878, 2018). "In addition, we also observed that YY1 mRNA expression was more highly expressed in tongue cancer than in the adjacent normal tissue." (PMID 29970878, 2018). "It would be necessary to explore in the future study whether or not the highly expressed YY1 in the tongue cancer would contribute to resistance of chemotherapy by cisplatin or other anticancer agents." (PMID 29970878, 2018).
abortion (1 paper, 2008). the ending of pregnancy by removing a fetus or embryo before it can survive outside the uterus. "Theoretically, all the genes whose promoters interact with SAP30 and/or YY1 could be a target for NSs/SAP30-dependent abnormal transcriptional regulation, possibly explaining some of the pathogenic effects due the virus such as abortion, hemorrhagic fever, hepatitis or encephalitis." (PMID 18225953, 2008).
angiomyolipoma (1 paper, 2013). A neoplasm with perivascular epithelioid cell differentiation often associated with tuberous sclerosis. "The mechanisms by which tuberin deficiency regulates kidney fibrosis in angiomyolipomas requires further study, including investigating the potential of YY1 that directly regulates several genes involved in fibrosis." (PMID 23705901, 2013).
autism spectrum disorder (1 paper, 2023). A spectrum of developmental disorders that includes autism, and Asperger syndrome. "YY1 and FOXP2 are involved in similar pathways of neural development, and both are associated with speech disorders and autism spectrum disorder." (PMID 37815922, 2023). "Haploinsufficiency of YY1 results in Gabriel-de Vreis syndrome, the symptoms of which are broad and primarily include developmental delay and intellectual disabilities such as autism spectrum disorder and language impairment." (PMID 37815922, 2023).
autoimmune disease (1 paper, 2020). A disorder resulting from loss of function or tissue destruction of an organ or multiple organs, arising from humoral or cellular immune responses of the individual to their own tissue constituents. "Yin yang 1 (YY1) is a transcription factor that regulates multiple complex biological functions, has recently gained attention as a mediator of autoimmune disease, and is over-expressed in both RA patients and CIA mice." (PMID 33364931, 2020).